CDK6 (cyclin dependent kinase 6)
Diseases named in the same sentence as CDK6 in open-access papers (continued):
Sharing a sentence is not in itself a finding about the gene and the disease.
tumor (continued). "CDK6 thus represents a factor that regulates tumor growth while also ensuring the supply of oxygen and energy to the tumor." (PMID 23948297, 2013). "We further identified CDK6 as a putative target of miR-105 which is likely a main contributor to the inhibition of tumour cell growth observed in our assays." (PMID 23950948, 2013). "We confirmed the reduced proliferation of Cdk6+/++Cdk6 cells in vivo by staining subcutaneous tumor sections for the proliferation marker Ki-67." (PMID 23948297, 2013). "In contrast, the correlation between CDK6 expression in tumor marginal regions and poor survival was significant, possibly because tumor recurrence usually originates in the residual tumor margin after tumor resection." (PMID 23594394, 2013). "The p16 protein exerts a tumor suppressor function by binding to the cyclin D1 CDK4/CDK6 complex, preventing the phosphorylation of the retinoblastoma (Rb) protein and resulting in G1 arrest." (PMID 24319475, 2013). "Tumor growth inversely correlated with the ability of the CDK6 construct to induce and/or bind to p16INK4a." (PMID 23948297, 2013). "The p16INK4A protein product of the CDKN2A locus is known to be an important tumor-suppressor gene, which directly inhibits the kinases encoded by the oncogenes CDK4 and CDK6." (PMID 24345474, 2013). "Analysis of survival data from patients with GBM reveals that, although elevated expression of CDK6 RNA in the tumor cores trended toward poor survivability, the results were not statistically significant." (PMID 23594394, 2013). "miR-124 exerts its tumor suppressor function by targeting cyclin-dependent kinase 6 (CDK6), and epigenetic silencing of miR-124 reportedly results in CDK6 activation and Rb phosphorylation." (PMID 24348513, 2013). "Because CDK6 promotes tumor growth while simultaneously guaranteeing the supply of oxygen and energy to the rapidly growing tumor, it enables tumor cells to proliferate extremely efficiently." (PMID 23948297, 2013). "Our data suggest that miR-145 exerts its tumor suppressor function by targeting c-Myc and Cdk6, leading to the inhibition of OSCC cell growth." (PMID 23710609, 2013). "The present study also demonstrates that expression of CDK6 antigen, particularly in the tumor margins, is prognostic of poor patient survival." (PMID 23594394, 2013). "CDK6 antigen expression was higher in tumor cores and margins than in adjacent normal brain tissues, and higher levels of CDK6 expression in the tumor margin correlated with decreased survival." (PMID 23594394, 2013). "Confirmation that p16INK4a is involved in CDK6’s tumor-suppressing role was obtained from experiments with p16INK4a/p19ARF-deficient animals and the CDK6R31C mutant unable to bind INK proteins." (PMID 23948297, 2013). "In contrast, patients with higher levels of CDK6 transcripts in the tumor margin had significantly poorer prognoses than those with submedian levels of CDK6 (P = 0.0279)." (PMID 23594394, 2013). "In some cells, Cdk1 has shown an anti-proliferative effect, and indeed it has been classified as a tumour suppressor, while in hematopoietic cells, Cdk6 is very abundant and essential for proliferation." (PMID 24312219, 2013). "The downregulation of CDK6 following miR-105 mimic overexpression in tumour cells would explain the effects on cell proliferation and invasion we see in our experiments." (PMID 23950948, 2013). "To better understand the tumor suppressive effect of miR-145 in oral tumorigenesis, particularly inhibition of cell growth, we investigate the effect of miR-145 on c-Myc and Cdk6 in the present study." (PMID 23710609, 2013).
tumor (continued). "A transgenic mouse model allowing the lymphocyte-specific activation of CDK6 activity showed increased p65 Ser536 phosphorylation and tumor formation." (PMID 23300567, 2012). "In most cases, the contribution of CDK6 to tumor phenotypes has been assessed in conjunction with CDK4, particularly in studies using PD332991 which inhibits both kinases." (PMID 23300567, 2012). "The consequence was inhibited tumor cell motility, reduced tumor growth, and inhibited metastasis formation, with an associated down-regulation of miRNA oncogenic target genes, such as C-MYC, E2F2, CDK6, and TGIF2." (PMID 23091478, 2012). "This predicts that increased abundance or activity of CDK6 will amplify both, inflammation and tumor progression." (PMID 23300567, 2012). "Tumor formation in thymi and spleens of v-cyclin transgenic mice correlated with increased levels of p65 Ser536 phosphorylation, increased expression of CDK6 and upregulaton of the NF-κB target cyclin D3." (PMID 23300567, 2012). "As CDK6 activity is known to be highest in G1 we also tested the requirement of CDK6 for p65 Ser 536 phosphorylation in synchronized tumor cells." (PMID 23300567, 2012). "The constitutive expression of E2F4 and CDK6 genes was increased in our study cohort of RB tumor tissues analyzed here." (PMID 23077401, 2012). "One of the previously identified targets mediating the tumour suppressive function of hsa-miR-124 is CDK6, via CDK6 mediated phosphorylation and subsequent inactivation of the tumour suppressor pRb." (PMID 20579385, 2010). "Notably, several target genes—including WNK1, CDK6, NCOA3, and NFAT5—are functionally linked to key oncogenic processes such as tumor growth, proliferation, and metastasis (eFigure 7A in Supplement 1)." (PMID 40737022, 2025). "They used the extraction of exosomal mRNA and detection of mRNA expression of candidate genes related to tumor progression or invasion, such as cyclin-dependent kinase 6 (CDK6), ras homolog family member U (RHOU), and spire type actin nucleation factor 2 (SPIRE2)." (PMID 40362297, 2025). "Additionally, H19 can promote tumor cell growth, invasion, and migration through the H19/miR-200a/CDK6/ZEB1 axis." (PMID 38715092, 2024). "Furthermore, recent studies have uncovered the impact of CDK6 on genomic stability and tumour immune microenvironment by regulating genes involved in the DNA replication and repair process and affecting the decisions of T cell fate." (PMID 38212482, 2024). "Furthermore, CDK6 mediated the suppression of the immune microenvironment to weaken anti-tumor immune responses." (PMID 39310261, 2024). "Since most drugs used for standard cytotoxic chemotherapy target the tumour cells during active proliferation, we hypothesised that patients with high levels of CDK6 expression may be more likely to benefit from chemotherapy." (PMID 38212482, 2024). "Our findings may now provide a mechanistic framework on the interplay between CDK4/CDK6 blockade and mTORi resulting in increased tumor control and prevent the acquisition of palbociclib resistance." (PMID 38954773, 2024). "Moreover, CDK6 expression is increased in many cancer types, and tumor progression is accompanied by enhanced activity of CDK6, suggesting that CDK6 is an attractive target for tumor therapy." (PMID 38626179, 2024). "Based on the tumor growth curve in nude and NSG mice, we speculated that Cdk6 deficiency may directly affect cancer cell proliferation independent of immune responses." (PMID 37833461, 2023).
tumor (continued). "Moreover, Western blot analysis showed that the CDK4 and CDK6 expressions were downregulated, whereas p21 expression was upregulated in tumor tissues from mice bearing QKI‐5 overexpressing cells compared with mice bearing control cells." (PMID 36172919, 2023). "The result showed that CDK6 expression was markedly higher in PC tumor tissues." (PMID 36457244, 2023). "CDK6 (cyclin-dependent kinase 6), as one of the proto-oncogenes driving tumors, has become a key target of various cancer therapies, and its inhibition can significantly affect tumor cell metabolism and antitumor immunity." (PMID 36639776, 2023). "This work reveals a function of both LRPPRC and CDK6 in tumor development and CDK4/6i resistance." (PMID 37452037, 2023). "However, CDK6 deletion in tumor cells resulted in significant tumor retard in both immunocompetent mice and immunodeficient mice." (PMID 37833461, 2023). "Overall, these findings supported that CDK6 plays an instrumental part in tumor immunity." (PMID 36457244, 2023). "Therefore, effective inhibition of CDK4/CDK6 expression can lead to cell cycle arrest, resulting in tumor growth suppression." (PMID 38049779, 2023). "Finally, we subcutaneously implanted control, Cdk6−/−, Cdk6−/−/Sting−/− and Cdk6−/−/Mavs−/− tumor cells to C57 mice and measured tumor size." (PMID 37833461, 2023). "As palbociclib inhibits both CDK4 and CDK6, we further addressed the effects of CDK6 on tumor growth and immunogenicity by analyzing online databases to determine whether CDK6 expression is related to the prognosis of patients." (PMID 37833461, 2023). "CDK6 is a key player in the cell cycle G1/S phase transition along with CDK4, and its aberrant activity and gene expression have been found to be associated with tumour progression in multiple human cancers." (PMID 37978493, 2023). "Additionally, in IHC experiments, GAA suppressed the expression of protein markers associated with tumor progression, including Ki67, CDK4, and CDK6." (PMID 37496051, 2023). "Moreover, like CDK2, CDK4/CDK6 exert oncogenic roles in this tumor type, especially in MYC-amplified forms." (PMID 36839989, 2023). "To examine whether CDK6 functionally drives self-renewal and tumor formation, we manipulated CDK6 expression in HCC cells using lentiviral-based knockdown and the CRISPR/dCas9-VP64-p65-Rta gene activation system (Dharmacon)." (PMID 37872167, 2023). "Besides, embelin, a CDK6 inhibitor, can regulate tumor immune microenvironment and inhibit tumor growth in PC." (PMID 36457244, 2023). "Deletion of Cdk4 or Cdk6 in tumor cells significantly reduce tumor growth." (PMID 37833461, 2023). "Tumours with RS1 were associated with an absence of ecDNA spanning CDK6 (log odds −1.18 p = 0.008) and low ME insertions (−1.14, p = 2.55 × 10-4)." (PMID 35396535, 2022). "Moreover, we analyzed CDK6 expression at different tumor stages (TNM tumor stages) in patients with PCa from the TCGA database." (PMID 35780240, 2022). "Moreover, we used immunohistochemistry (IHC) to evaluate the expression levels of c-fos, CDK6, and cyclin D1 in the tumor tissues." (PMID 35444864, 2022). "Furthermore, researchers found that pharmacological inhibitors of cyclin-dependent kinase 4 (CDK4) and CDK6 boost tumor immunogenicity." (PMID 36304306, 2022). "Cyclin-dependent kinase CDK4 and CDK6 are hyperactivated in various tumor." (PMID 36376832, 2022). "Our study supports the clinical development of therapeutic strategies co-targeting ER, CDK4/6 and CDK2 following progression on AI-monotherapy or combined CDK4/6i and ET to improve survival of patients exhibiting high tumor levels of CDK6, p-CDK2, and/or cyclin E1." (PMID 36153348, 2022). "Evidence suggests CDK6 enhances tumor cell growth by regulating FOXM1." (PMID 36548336, 2022). "Developing small inhibitors based on CDK4/CDK6 is an alternative approach in tumor treatment." (PMID 36376832, 2022).
tumor (continued). "Interestingly, we also found that CDK6 was significantly upregulated upon PAIP1 knockdown in SMMC-7721 xenograft tumor cells, suggesting that PAIP1 negatively regulates CDK6 expression in HCC cells." (PMID 36436074, 2022). "RB1 is a well known tumor suppressor involved in CDK4/CDK6-dependent cell-cycle regulation." (PMID 34943047, 2021). "The results showed that the nanoparticles could improve the expression of miR-34 in the cells, and then regulate the expression of Bcl-2, Cdk6 and CyclinD1, and play the inhibitory effect of miR-34a on the proliferation and migration of tumor cells." (PMID 34696703, 2021). "In vivo T cell-intrinsic loss of CDK6 reduces numbers of tumor-infiltrating CD4+ T cells and Tregs without affecting tumor growth." (PMID 34248938, 2021). "CDK4/CDK6 inhibitors possibly instigate an antitumor immune response by the stimulation of the T lymphocyte activation effector, reduce T cell proliferation, and enhances tumor cell antigen presentation." (PMID 34361615, 2021). "The CDK4-specific effect of palbociclib on displacing p21 from cyclin D1-CDK4-p21—but not from cyclin D1-CDK6-p21—suggests that the relative ratio of CDK4 to CDK6 within a tumor may dictate drug sensitivity and resistance." (PMID 34099663, 2021). "Further, these studies suggest that inhibition of CDK4 and CDK6 could be exploited to specifically control the proliferation of tumor cells that rely on their activity." (PMID 34204543, 2021). "However, the possible radiosensitizing effects of the cyclin-dependent kinase 4 (CDK4) and cyclin-dependent kinase 6 (CDK6) inhibitor palbociclib are not limited to tumor cells alone, but can also affect healthy cells." (PMID 34722291, 2021). "We here show that T cell-intrinsic loss of CDK6 does not suffice to cause enhanced anti-tumor immunity against MC38 tumors in vivo." (PMID 34248938, 2021). "MiR-124 acts as a tumor suppressor through regulation of cyclin D1 and cyclin-dependent kinase 6 (CDK6), which may serve as a potential therapeutic target in HCC." (PMID 34771525, 2021). "Moreover, CDK6 has directly involved in transcription in tumor cells and hematopoietic stem cells in addition to the kinase activity with CDK4 in cell-cycle progression." (PMID 33925607, 2021). "We wondered what caused the discrepancy between the impaired IFN signaling and reduced T cell expansion and the absence of any effects upon virus or tumor challenge in vivo upon T cell-intrinsic loss of CDK6." (PMID 34248938, 2021). "In addition, cell cycle–related proteins, including CDK4/CDK6 and cyclin D1 were up-regulated upon tumor onset in thymi harboring small tumors, which was maintained in end-stage tumors for most of the samples tested." (PMID 33310759, 2021). "Further in vivo and in vitro experiments demonstrated that miR-124, acting as a tumor suppressor, inhibited tumor cell growth by targeting cyclin-dependent kinase 6 (CDK6), which is a member of the family of serine-threonine kinases that promotes cell cycle progression." (PMID 34552822, 2021). "In conclusion, UAP1L1 was reported to be a tumor promotor in the development and progression of GC which may exert its role through regulating CDK6 and may act as a candidate of therapeutic target in treatment." (PMID 32310823, 2020). "AP-1 transcription factors might thereby represent the link between the MAPK pathway and CDK6 to enable the crosstalk between these programs contributing to transformation and tumor maintenance." (PMID 33255177, 2020). "Notably, miR-138-5p was downregulated in HCC and acted as a tumor suppressor to inhibit several cell cycle-related genes such as CDK6." (PMID 33121524, 2020).
tumor (continued). "The miR-15a/16-1 cluster directly down-regulates the anti-apoptotic protein BCL-2, MCL-1, CCND1, and WNT3A and leads to induction of G0G1 arrest in tumor cells by suppressing cell cycle-positive regulators including CDK6 (Cyclin Dependent Kinase 6), Cyclins D and E." (PMID 32549409, 2020). "Studies showed that CDK4/CDK6 inhibition promoted apoptosis in tumor cells." (PMID 32860670, 2020). "In addition, the function of CDK6 as transcriptional regulator interferes with tumor progression at multiple levels." (PMID 33255177, 2020). "Moreover, western blotting demonstrated the downregulated expression of UAP1L1 and CDK6, and upregulated expression of E-cadherin and ZO-1 in tumor tissues collected from shUAP1L1 group." (PMID 32310823, 2020). "CDK6 serves as the target of multiple miRNAs and had demonstrated important roles in tumor growth." (PMID 32127798, 2020). "Copy number analysis indicated gain in CDK4 (25.7%) and CDK6 (14.7%) in CCA tumor samples." (PMID 33116269, 2020). "miR-1296-5p acts as a tumor suppressor, at least partly, by targeting CDK6 and EGFR." (PMID 30530570, 2019). "In addition, comparative qPCR analysis of the tumor samples showed that the combination treatment resulted in the lowest level of CDK6, β-catenin, Sox2 and lncSNHG15." (PMID 31462285, 2019). "In addition, a reduction of Cdk6 transcripts is observed in Wnt7b knockout tumour cells, which can be restored by WNT3a supplementation." (PMID 30926782, 2019). "Hence, we checked the molecular interaction between tumor-associated proteins such as AKT, PI3K, mTOR, and cell cycle regulating proteins such as CHK1, CHK2, CDK6, Cyclin D1, and proteins from MAPK signaling including MEK1, p38MAPK, and SAPK/JNK." (PMID 31783627, 2019). "CDK6 has been shown to be a tumor promoter in many types of cancers." (PMID 30530570, 2019). "Furthermore, we showed that CDK6 expression was significantly upregulated in GC tissues compared to non-tumor tissues both in mRNA and protein levels." (PMID 30733646, 2019). "We were also intrigued by the fact that CDK6 but also CDK4 interfered with tumor angiogenesis." (PMID 30858922, 2019). "Tumour-derived chromosomal copy number changes (1p, 4q loss and 13q gain) and copy number changes of driver alterations including ERBB2 and CDK6 were detected in cfDNA of colorectal and breast cancer patients with good concordance rates when tumour tissue was available for analysis." (PMID 31817150, 2019). "In contrast, our findings show that copanlisib suppresses tumor growth in HCC cells mainly by triggering a G1 cell cycle arrest by inhibiting the cyclin D1/CDK4/CDK6 axis, without causing apoptosis." (PMID 30962952, 2019). "Furthermore, the patient’s tumor harbored amplifications of BRAF, EGFR, MET, and CDK6, which provides a rationale for this tumor’s acquired resistance to the triple BRAF/MEK/CDK4&6 inhibitor treatment applied before sequencing." (PMID 30373609, 2018). "For example, our core mRNA signature included tumor-suppressor genes CDK6 and RB1." (PMID 30404194, 2018). "We suggest that PLA2R1-regulated expression of FN1, TWIST1, and CDK6 might be accountable for the cell type-dependent impact of PLA2R1 in tumour cell survival and growth." (PMID 30542512, 2018). "Emerging evidence suggests that certain tumour cells require CDK6 for proliferation." (PMID 30517191, 2018). "Microarray analysis revealed the CDKN2A and CDKN1A genes to be significantly repressed in all tumour types vs controls while the CDK2 gene was upregulated in the all tumours vs controls and CDK6 was also upregulated in GH-secreting tumours vs controls (data not shown)." (PMID 28649092, 2017). "Mechanically, we found that hsa_circ_000984 may act as a competing endogenous RNA (ceRNA) by competitively binding miR-106b and effectively upregulate the expression of CDK6, thereby inducing a series of malignant phenotypes of tumor cells." (PMID 29207676, 2017).